ID4 (inhibitor of DNA binding 4)
Diseases named in the same sentence as ID4 in open-access papers (continued):
Sharing a sentence is not in itself a finding about the gene and the disease.
leukemia (7 papers, 2007 to 2020). A malignant (clonal) hematologic disorder, involving hematopoietic stem cells and characterized by the presence of primitive or atypical myeloid or lymphoid cells in the bone marrow and the blood. "Our investigation by testing the follow‐up paired patients (MDS to AML and CP/AP‐CML to BC‐CML) indicated that ID4 methylation was associated with leukaemia transformation in MDS and disease progression in CML." (PMID 28452111, 2017). "The results revealed that ID4 hypermethylation was associated with the increased risk of leukemia (P<0.00001, OR = 45.24, 95% CI = 11.02–185.78)." (PMID 24810788, 2014). "In our results of analysis, the aberrant DNA methylation at ID4 gene was a risk factor for leukemia, especially for AML." (PMID 24810788, 2014). "However, ID4 hypermethylation correlated with shorter OS and leukaemia‐free survival (LFS) time and acted as an independent risk factor affecting OS in acute myeloid leukaemia (AML)." (PMID 28452111, 2017). "Aberrant methylation of the ID4 promoter region is associated with invasiveness, growth, and recurrence of many solid tumors and with initiation and progression in hematological cancers including leukemia and lymphoma." (PMID 25889027, 2015). "The ID4 gene, which was also reported to be down-regulated in gastric adenocarcinoma and leukemia, may cause the alteration of the TGF-beta signaling pathway which regulates the growth and proliferation of cells, blocking the growth of many different cell types." (PMID 19458770, 2007). "Emerging evidence showed that ID4 was direct target of miR-335, acting as a tumor suppressor in leukemia." (PMID 31147526, 2019). "Previously, it was shown that both bone marrow blasts and ID4 methylation were independent factors for leukemia-free survival (LFS) estimation in MDS patients." (PMID 25889027, 2015). "Moreover, aberrant miR-335/ID4 expression independently affected chemotherapy response and leukemia-free/overall survival in patients with AML." (PMID 31147526, 2019). "A further subgroup meta-analysis by subtype of leukemia showed that CDKN2A, CDKN2B, ID4 genes were significantly hypermethylated in acute myeloid leukemia." (PMID 24810788, 2014).
lung adenocarcinoma (7 papers, 2019 to 2023). A carcinoma that arises from the lung and is characterized by the presence of malignant glandular epithelial cells. "Therefore, Id4 may serve as a marker for identifying high-risk patients and as a potential therapeutic target for the treatment of lung adenocarcinoma." (PMID 31847356, 2019). "ID4 is a tumor metastasis suppressor regulating EMT in lung adenocarcinoma, increasing cell apoptosis, and inhibiting cell proliferation through S-phase progression arrests." (PMID 36661515, 2023). "ID4 (inhibitor of DNA binding 4) is a tumor suppressor that inhibits epithelial–mesenchymal transition and metastasis and induces apoptosis in lung adenocarcinoma through the activation of the p38 MAPK signaling pathway." (PMID 36101460, 2022). "On the other hand, miR-9-5p, which was also found to be upregulated in BM, promotes cancer cell progression by silencing ID4 in lung adenocarcinoma cell lines." (PMID 36613642, 2022). "Because ID4 functions as a tumor suppressor in lung adenocarcinoma, we examined whether ID4 is a downstream target of ELK3 in TNBC." (PMID 38188675, 2023). "Furthermore, ID4 was significantly down-regulated in lung adenocarcinoma in the Okayama, Beer, Landi, Su, Garber, Stearman and Hou datasets, and also in squamous cell lung carcinoma (Garber and Hou datasets)." (PMID 32003423, 2020). "Therefore, we explored whether the expression of Slug could be interfered with by the manipulation of Id4 expression in lung adenocarcinoma cells." (PMID 31847356, 2019). "According to our results, we could indicate that enhancing the expression of Id4 reduced the cell invasive ability in both CL1-5 and H1299 lung adenocarcinoma cell lines, for which the Id4 expression belongs to a relatively lower baseline." (PMID 31847356, 2019).
endometriosis (6 papers, 2017 to 2023). The growth of functional endometrial tissue in anatomic sites outside the uterine body. "Among the top 20 genes, APOE, DUSP1, MGST1, G0S2, ID4, WEE1, and H2AFZ expression levels were upregulated in the oocytes of patients with endometriosis." (PMID 33467661, 2021). "We found 11 loci showing nominal association (P < 1.0 × 10−6), 3 of which were established endometriosis loci (WNT4, CDKN2BAS1, ID4) and 8 had not previously been reported." (PMID 28333195, 2017).
pancreatic cancer (6 papers, 2019 to 2024). "SNHG7 promotes the proliferation of pancreatic cancer cells through ID4 by competitively binding miR‐342‐3p." (PMID 32892482, 2020). "It has been reported that lncRNA SNHG7 promotes cell proliferation, migration and invasion in pancreatic cancer by sponging miR-342-3p and targeting ID4." (PMID 32370736, 2020). "In pancreatic cancer, SNHG7 is highly expressed, and the knockdown of this gene inhibits tumor progression through the miR-342-3p/ID4 axis." (PMID 39195675, 2024).
astrocytomas (5 papers, 2005 to 2024). "The malignant transformation of astrocytomas, is associated with augmented ID expression, particularly ID4." (PMID 23613880, 2013). "Nevertheless, the increased ID4 expression level in diffusely infiltrative astrocytoma is in accord with the tumor re-expression model of IDs, postulating ID4 as an additional marker of astrocytoma progression in malignancy." (PMID 23613880, 2013). "Genes upregulated in astrocytomas include ID4, CD74 and FOS." (PMID 36865335, 2023). "Gene expression analysis by qRT-PCR for ID4 showed higher median expression levels in all diffusely infiltrative astrocytoma cases (AGII to GBM) relative to the NN cases, and comparison among the groups was statistically significant (p<0.0005, Kruskall-Wallis test)." (PMID 23613880, 2013). "In bladder cancers, both ID4 and SOX4 were amplified and overexpressed heterogeneously, similar to astrocytomas, and contributed to the variable biological and clinical behavior of the tumors." (PMID 23613880, 2013). "This pattern was maintained in secondary GBM and further confirmed by immunohistochemistry, suggesting a role for ID4, SOX2 and SOX4 in early astrocytoma tumorigenesis." (PMID 23613880, 2013). "Together with the positive correlation between OCT-4 and ID4 found in both AGIII and GBM cases, these data indicate a role for this target in the most malignant grades of astrocytoma." (PMID 23613880, 2013). "Our study demonstrated significantly higher mRNA expression levels of ID4 in astrocytomas when compared to non-neoplastic brain tissue." (PMID 23613880, 2013). "Furthermore, the magnitude and the timing of Id4 induction could explain the heterogeneity of OAC, in that one group is genetically related to ODG, and the other one related to astrocytomas." (PMID 16018821, 2005).
colon carcinoma (5 papers, 2005 to 2022). "Solid tumors, including breast, gastric and colon cancer, as well as myelodysplasia are associated with ID4 methylation and silencing." (PMID 23285167, 2012). "Conversely, ID4 expression has been reported to be down-regulated by promoter hypermethylation in colon carcinomas." (PMID 15876350, 2005). "Though CDC42 was reported highly expressed in colon cancer and was downregulated by the potential tumor suppressor gene ID4, its role in the metastasis of colon cancer is still unknown." (PMID 36146640, 2022).
thyroid cancer (5 papers, 2014 to 2024). "It is noteworthy that the last study showed novel loci containing genes that were previously implicated in thyroid cancer (e.g., HES1, SPATA13, DIRC3, ID4) and a positive association of TSH with VEGFA expression, therefore angiogenesis." (PMID 39767631, 2024). "ID4 is a promising target in cancer therapy and it could be involved in thyroid tumorigenesis and prevent thyroid cancer invasion and metastasis." (PMID 34721037, 2021). "However, the expression levels of ID1, ID3, and ID4 were downregulated in thyroid cancer." (PMID 38195969, 2024).
bladder cancer (4 papers, 2005 to 2024). "In contrast, ID4 expression has probably to be considered as ectopic in bladder cancer, since it is normally restricted to other tissues including testes and brain." (PMID 15876350, 2005). "In the present study, we have therefore investigated to which extent ID4 gene copy numbers and expression are affected by 6p22 amplifications in bladder cancer, in comparison to E2F3 and DEK." (PMID 15876350, 2005). "In conclusion, our study indicates that the 6p22.3 amplification prevalent in advanced bladder cancers is highly heterogeneous and contributes to the altered expression of several genes, including ID4, in a highly variable manner." (PMID 15876350, 2005). "ID4 is a potential oncogene in a small subset of bladder cancers." (PMID 15876350, 2005). "However, the ID4 gene may act as a proto-oncogene, either being highly expressed in tumor tissue or exhibiting an increased copy number in bladder cancer." (PMID 38443680, 2024).
chronic lymphocytic leukemia (4 papers, 2012 to 2017). "Epigenetic silencing of Id4 in leukemia, breast, colorectal mouse and human chronic lymphocytic leukemia (CLL), and gastric cancer tend to support its anti-tumor activity." (PMID 23342267, 2012). "Epigenetic silencing of Id4 in leukemia, breast, colorectal mouse and human CLL (chronic lymphocytic leukemia) and gastric cancer tend to support its anti-tumor activity." (PMID 23786676, 2013). "Majority of studies have demonstrated tumor suppressor activity of Id4 which is largely based on the evidence that it is epigenetically silencing in cancers such as leukemia, breast, colorectal mouse and human CLL (chronic lymphocytic leukemia) and gastric cancer." (PMID 24330748, 2013).
lymphoma (4 papers, 2008 to 2020). A malignant (clonal) proliferation of B- lymphocytes or T- lymphocytes which involves the lymph nodes, bone marrow and/or extranodal sites. "Moreover, by the functional experiments in vitro, restoration of ID4 expression inhibited cell proliferation through cell cycle arrest and promoted cell apoptosis in accordance with previous studies in mouse lymphoma Yac‐1 cells." (PMID 28452111, 2017). "Id4 methylation has been found to be high in lymphoma tissues, whereas no methylation has been detected in control tissues." (PMID 28122577, 2017).
melanoma (4 papers, 2015 to 2018). A malignant, usually aggressive tumor composed of atypical, neoplastic melanocytes. "As is the case with other common melanoma markers, ID4 was also detectable in benign nevi, albeit at lower levels." (PMID 25642713, 2015). "Intense and pervasive ID4 protein expression was detected in human melanoma tissue samples, suggesting disease relevance for this protein." (PMID 25642713, 2015). "The fraction of human melanoma tumor cells expressing ID4 was very high, and this is generally consistent with our tissue culture model, where a majority of cells can acquire high ID4 expression under specific conditions." (PMID 25642713, 2015). "We suggest that ID4 is upregulated in melanoma as part of a stem cell-like program that facilitates further adaptive plasticity." (PMID 25642713, 2015). "Here we show that high levels of ID4 protein are present in human melanoma tissue samples and siRNA-based knockdown of ID4 in cultured melanoma cells promoted progression to a highly differentiated, more normal cell state." (PMID 25642713, 2015). "MBOAT1 is related to lipid biosynthesis and still poorly described, while ID4 role in melanoma is more documented and may take part in phenotypic switch of melanoma cells." (PMID 29963229, 2018). "The comparative analysis of monolayer vs 3D spheroid showed that neural progenitor genes that includes ID4 (Inhibitor of DNA Binding 4) switched from 3D-spheroid to highly differentiated morphology indicating that ID4 plays a crucial role in the maintenance of CSCs phenotype in melanoma cells." (PMID 28137308, 2017). "The melanoma stem cell-like state may be protected by factors such as ID4, thereby potentially identifying a new therapeutic vulnerability to drive differentiation to the normal cell phenotype." (PMID 25642713, 2015). "In summary, in this work we used a melanoma cell line-based system to study processes that occur as melanoma cells move on the axis between stem cell-like and proliferative states, and identified ID4 as having a functional role in phenotype-switching." (PMID 25642713, 2015). "Indeed, a major finding of our work is that ID4 is highly expressed in a large fraction of melanoma tissues." (PMID 25642713, 2015). "ID4 may contribute to disease by preventing stem cell-like melanoma cells from progressing to a normal differentiated state." (PMID 25642713, 2015). "Disabling of ID4 leads to differentiation of human melanoma cells." (PMID 25642713, 2015). "We hypothesize that the developmental function of the ID4 gene as an inhibitor of differentiation is being exploited as a restrictive factor by melanoma cells to inhibit widespread terminal differentiation." (PMID 25642713, 2015). "Our current study suggests that oncogenic ID4 may very well constitute a putatively novel melanoma target." (PMID 25642713, 2015). "Our findings support a model whereby melanoma stem cell-like cells can be pervasive, and serve as advantageous plastic intermediates, possibly for generating heterogeneous tumor cells; furthermore, the stem cell-like state must be protected by factors such as ID4 that prevent normal differentiation." (PMID 25642713, 2015). "3D-MBs showed strong staining with antibodies against NOTCH and ID4, as well as NESTIN, a neural progenitor cell factor known to be variably expressed in 1205Lu cells and other melanoma cell lines." (PMID 25642713, 2015). "A few genes located nearby the most significantly associated SNPs in this study have been described as involved in melanoma tumor biology (CKAP4, ID4, SATB1, and PLEKHA5), but not in melanoma susceptibility." (PMID 29963229, 2018). "As opposed to the nuclear ID4 staining seen in these cancers, melanoma tissues showed largely cytoplasmic ID4 staining." (PMID 25642713, 2015). "Similar, although less dramatic phenotypic changes were observed in other melanoma cell lines after ID4 shRNA treatment (data not shown)." (PMID 25642713, 2015).
melanoma (continued). "Melanoma cells maintained in the stem cell-like state showed a striking upregulation of a gene set related to development and neural stem cell biology, which included SRY-box 2 (SOX2) and Inhibitor of DNA Binding 4 (ID4)." (PMID 25642713, 2015). "The microarray results indicated that microenvironmental cues can trigger switching of melanoma cells to a neural stem cell-like pattern, as six genes related to neural stem cell and neural stem cell niche biology were upregulated: SOX2, ID4, GFRA2, S100A4, LGI4, and GJB1." (PMID 25642713, 2015).
myelodysplastic syndrome (4 papers, 2015 to 2022). A clonal hematopoietic disorder characterized by dysplasia and ineffective hematopoiesis in one or more of the hematopoietic cell lines. "ID4 hypermethylation was an independent factor that affected clinical outcome and predicted leukemic transformation in patients with myelodysplastic syndrome (MDS)." (PMID 36443709, 2022). "Id4 methylation plays an important role in disease progression in patients with myelodysplastic syndrome (MDS) that is a myeloid hematopoietic malignant disorder with high susceptibility to transform into AML." (PMID 28122577, 2017). "ID4 hypermethylation was associated with higher IPSS scores, but was not an independent prognostic biomarker affecting overall survival (OS) in myelodysplastic syndrome (MDS)." (PMID 28452111, 2017).
lymph node metastasis (3 papers, 2008 to 2021). "Zhou and colleagues recently evaluated the prognostic relevance of the ID family by using a set of public databases and reported that higher mRNA levels of ID1 and ID4 were associated with lower histological grades, less lymph-node metastasis, and longer survival rates." (PMID 33514024, 2021). "Interestingly, ID4 promoter methylation was a factor for unfavourable recurrence-free survival (P=0.036) and increased risk for lymph node metastasis (P=0.030)." (PMID 18513385, 2008).
squamous cell carcinoma (3 papers, 2020 to 2021). A carcinoma arising from squamous epithelial cells. "Promoter of ID4 exhibits significantly increased methylation accompanied by loss of gene expression in squamous cell carcinoma compared to normal skin." (PMID 33133131, 2020).
acute leukemia (2 papers, 2019). A clonal (malignant) hematopoietic disorder with an acute onset, affecting the bone marrow and the peripheral blood. "It has also been demonstrated that in patients with acute leukemia, when compared with the dual vacuity of the Qi and Yin syndrome, ID4 gene methylation is more likely to occur in patients with toxic hot flaming syndrome and static blood and binding phlegm syndrome." (PMID 31772596, 2019).
astrocytic tumor (2 papers, 2013 to 2022). A glial tumor of the brain or spinal cord showing astrocytic differentiation. "Structural differences of Id4 might explain its unique function, compared to Id1–Id3 in astrocytic tumors, as Id4 has a unique polyalanine domain at the N-terminus and a polyproline domain at the C-terminus, which could convey specificity for the Id4/Twist1 interaction." (PMID 34302526, 2022).
benign prostate hyperplasia (2 papers, 2009 to 2021). "Collective results suggested that Id4-/- knockout (KO) mice display complex phenotypes that resemble or mimic Pten and Nkx3.1 combined KO in many respects but with no clear cancerous phenotype or prostatic hyperplasia observed in Nkx3.1+/-;Pten+/- or Nkx3.1-/- mice respectively." (PMID 33884281, 2021).
cervical cancer (2 papers, 2020 to 2021). A primary or metastatic malignant neoplasm involving the cervix. "In the present study, EPB41L3 and ID4 had a possibility of 7% mutation in cervical cancer, so we speculated that the mutation led to the aberrant methylation or deregulation of both genes." (PMID 32368784, 2020). "Furthermore, hypermethylation of EPB41L3 and ID4 may suppress the development of cervical cancer." (PMID 32368784, 2020). "Ten genes validated with the TCGA database, including five DMGs (ESR1, EPB41L3, EDNRB,ID4, PLAC), might be used as biomarkers and therapeutic targets in the precise diagnosis and treatment of cervical cancer." (PMID 32368784, 2020).
gastric adenocarcinoma (2 papers, 2007 to 2008). "The ID4 promoter region contains also CpG islands which were found to be hypermethylated in gastric adenocarcinomas in association with gene silencing." (PMID 18513385, 2008).